LIPG (lipase G, endothelial type)
Diseases named in the same sentence as LIPG in open-access papers (continued):
Sharing a sentence is not in itself a finding about the gene and the disease.
breast carcinoma (continued). "A study has shown that severe oxidative stress triggers endothelial lipase (LIPG) upregulation, which induces the lipolysis of extracellular lipoproteins, to compensate the ROS-impeded fatty acid synthesis pathway in breast cancer cells, thus supporting tumor progression." (PMID 34405016, 2021). "This analysis has revealed a number of intact transcripts that are massively upregulated by recurrent geneUIB fusions, including IGF2 in colorectal, ETV1 in prostate, IGF2BP3 in thyroid, and ANO3, LIPG, FUT5, and RSG9 in breast cancers (ordered by the expression fold change within a tumor type)." (PMID 32631391, 2020). "We found that XEN445 preferentially inhibited the proliferation of LIPG-expressing TNBC cells but not LIPG-negative luminal breast cancer cells." (PMID 32488004, 2020). "If this is true, inactivating both enzymatic and non-enzymatic functions of LIPG will be essential for inhibiting the whole oncogenic function of LIPG in breast cancer." (PMID 32488004, 2020). "Our previous studies have shown that LIPG also possesses both enzymatic and non-enzymatic functions in breast cancer cells." (PMID 32488004, 2020). "Due to these potential facts and the unknown function of DTX3L in breast cancer, we performed DTX3L knockdown studies to reveal its role in LIPG signaling in basal-like TNBC cells." (PMID 29350614, 2018). "Currently, there are no therapeutic LIPG inhibitors available for breast cancer patients." (PMID 35954428, 2022). "Plasma levels of LIPG may show, based on the results of this and previous studies, opposing effects on cancer, decreasing or increasing the risks, similar to what is seen with NLR and gastric and breast cancer in previous studies." (PMID 34001944, 2021).
atherosclerosis (13 papers, 2012 to 2025). A disease characterized by the build-up of fatty material and calcium deposition in the arterial wall resulting in partial or complete occlusion of the arterial lumen. "Between the genes differentially expressed in both comparisons (MI+RTX vs. MI and MI vs. control), we found lipase G, endothelial type (LIPG) is an enzyme that plays a key role in both atherosclerosis and oncogenesis." (PMID 37588971, 2023). "In detail, endothelial lipase (EL; LIPG) plays a key role in atherosclerosis, and is actively investigated as a modulator in inflammatory processes and cancer, with examples of inhibitors of natural origin targeting closely related triacyglycerol lipases." (PMID 33546180, 2021). "Interestingly, in an animal model of atherosclerosis, LIPG expression is enhanced in the aorta and reduced in the liver of mice developing atherosclerosis." (PMID 35614477, 2022). "Moreover, patients with atherosclerosis have high levels of LIPG expression." (PMID 37588971, 2023). "LIPG regulates the circulating level of HDL-C and also trough non-enzymatic action can increase cellular lipoprotein uptake and monocyte adhesion and contribute to atherosclerosis." (PMID 23675527, 2013).
coronary artery disease (10 papers, 2014 to 2025). "Several studies have investigated a potential association between the endothelial lipase gene (LIPG) 584C/T polymorphism and susceptibility to coronary artery disease (CAD), but a uniform conclusion is yet to be reached." (PMID 32893849, 2020).
triple-negative breast carcinoma (8 papers, 2018 to 2025). An invasive breast carcinoma which is negative for expression of estrogen receptor (ER), progesterone receptor (PR), and human epidermal growth factor receptor 2 (HER2). "It has also been shown that overexpression of an oncogenic form of HER2 leads to strong expression of LIPG31 and LIPG has been reported to be associated with tumor growth 15 and with metastasis in triple-negative breast cancer." (PMID 34001944, 2021). "Endothelial Lipase (LIPG): ISGylation mediated by Deltex-3-like E3 ubiquitin ligase (DTX3L) prevents LIPG ubiquitin-dependent degradation, promoting tumourigenicity and metastasis in triple-negative breast cancer (TNBC)." (PMID 40103488, 2025). "In triple-negative breast cancer (TNBC) cells, we find that the expression of LIPG is associated with long non-coding RNA DANCR and positively correlates with gene signatures of mitochondrial metabolism-oxidative phosphorylation (OXPHOS)." (PMID 35954428, 2022). "Our previous studies have revealed that LIPG overexpression is required for tumor formation and metastasis of human basal-like triple-negative breast cancer (TNBC)." (PMID 32488004, 2020). "Overexpression of LIPG increases intracellular triglyceride content in HAEC cells and promotes proliferation of triple-negative breast cancer cells." (PMID 39946436, 2025). "DTX3L, an E3-ubiquitin ligase, is required for maintaining LIPG protein levels by inhibiting proteasome-mediated LIPG degradation, and DTX3L-LIPG-ISG15 signaling is essential for malignancies of triple-negative breast cancer cells (TNBCs)." (PMID 35159348, 2022).
gastric cancer (7 papers, 2011 to 2025). A primary or metastatic malignant neoplasm involving the stomach. "There was approximately a tenfold average decrease in the LIPG expression levels in urine samples of stomach cancer compared to healthy individuals, producing an AUC of 0.96714." (PMID 34001944, 2021). "Notably, ABCG1 has been reported as a diagnostic marker in clear cell renal cell carcinoma, and LIPG in gastric cancer." (PMID 40804485, 2025).
myocardial infarction (6 papers, 2012 to 2022). Gross necrosis of the myocardium, as a result of interruption of the blood supply to the area, as in coronary thrombosis. "An MR study used variants in the LIPG gene, encoding hepatic lipase, as an instrument for HDL-C and examined its relationship with myocardial infarction (MI) risk." (PMID 27342221, 2016). "A recent analysis using a Mendelian randomisation approach showed that lifelong exposure to higher plasma levels of HDL cholesterol among carriers of the loss-of-function endothelial lipase genetic variant (LIPG Asn396Ser) did not translate to reduction in myocardial infarction (MI) risk." (PMID 24460800, 2014).
Obesity (6 papers, 2011 to 2025). Accumulation of substantial excess body fat. "In the placenta, LIPG expression is diminished in obesity, suggesting sensitivity to maternal metabolic status." (PMID 41273236, 2025).
Hypertension (5 papers, 2016 to 2025). The presence of chronic increased pressure in the systemic arterial system. "For example, hypertension regulates LIPG's activity which can hydrolyze the fatty acid from both PCs and LPCs." (PMID 37328862, 2023). "Many reports showed that CETP, LIPC and LIPG were associated with HDL and LDL and that MTHRR had known main effects for LDL and blood pressure, NR1I3 for lipid metabolism, PLTP for LDL, FOXO1 for LDL and hypertension, SMAD9 for hypertension, and CSMD1 for SBP." (PMID 27104857, 2016). "ANGPTL4 and LIPG PTV carriers in turn had lower risks of hypertension compared to noncarriers." (PMID 33909604, 2021).
metabolic syndrome (5 papers, 2017 to 2025). A cluster of metabolic risk factors for CARDIOVASCULAR DISEASES and TYPE 2 DIABETES MELLITUS. "LIPG has been implicated in metabolic disorders, for instance, being identified as a pro‐atherogenic factor in metabolic syndrome." (PMID 41273236, 2025). "As blocking LIPG activity leads to an increase in total plasma HDL levels, inhibition of LIPG activity has emerged as a potential therapeutic strategy for the treatment of dyslipidemia-related cardiovascular disease." (PMID 32488004, 2020).
breast tumor (3 papers, 2016 to 2023). "All together, these observations make LIPG activity an Achilles heel of luminal and, more importantly, of triple negative/basal-like breast tumours, for which limited therapeutic options are currently available." (PMID 27045898, 2016).
hyperlipidemia (3 papers, 2021 to 2025). "To assess whether localized enrichment of CD36 and LIPG at the LOSS region is associated with elevated lipid metabolism, we exposed mice to acute hyperlipidemia using oral gavage of olive oil." (PMID 39234692, 2024).
Insulin resistance (3 papers, 2016 to 2025). Increased resistance towards insulin, that is, diminished effectiveness of insulin in reducing blood glucose levels. "Under insulin resistance, this LIPG-mediated free fatty acids release may exacerbate hepatic TG deposition and link to NAFLD pathogenesis." (PMID 41300406, 2025).
leukemia (3 papers, 2022 to 2025). A malignant (clonal) hematologic disorder, involving hematopoietic stem cells and characterized by the presence of primitive or atypical myeloid or lymphoid cells in the bone marrow and the blood. "For example, the liver microenvironment triggers metabolic changes by increasing the expression of endothelial lipase (LIPG) in leukemia cells." (PMID 40302792, 2025). "Recent studies have shown that lipid metabolism and other metabolic abnormalities occur in AML mice, and the expression of endothelial lipase (LIPG) was increased in leukemia cells of AML mice, LIPG might be a potential target for the abnormal lipid metabolism in AML." (PMID 36193167, 2022).
viral infection (3 papers, 2016 to 2025). "Our previous work implicated endothelial lipase (LIPG) as a host factor promoting HBV entry, and we subsequently discovered that Netrin-1 interacts with LIPG and recombinant Netrin-1 suppressed the viral infection." (PMID 41406170, 2025). "Our further analysis demonstrated that IFITM2, KMO, LIPG genes exerted the most obvious inhibition against viral infections in this study." (PMID 35235615, 2022).
colorectal cancer (2 papers, 2022 to 2024). A primary or metastatic malignant neoplasm that affects the colon or rectum. "We identified the 500 most highly co-expressed genes with LIPG by gene expression correlation analysis utilizing the GSE97023 dataset (n = 34), upon which genome-wide expression analyses on 34 colorectal cancer cell lines were performed." (PMID 35108261, 2022).
hepatoma (2 papers, 2023 to 2025).
hyperalphalipoproteinemia (2 papers, 2012 to 2025). An autosomal dominant genetic condition caused by mutation(s) in the CETP gene, encoding cholesteryl ester transfer protein. "•A rare heterozygous variant in the LIPG gene causes hyperalphalipoproteinemia." (PMID 40703622, 2025). "Taken together, we show that rare coding and splicing mutations in LIPG, CETP, and GALNT2 are enriched in persons with hyperalphalipoproteinemia and segregate with elevated HDLc in families." (PMID 22952570, 2012).
hypertriglyceridemia (2 papers, 2014 to 2023). A laboratory test result indicating elevated triglyceride concentration in the blood. "Additionally, LIPG’s concentration was reported positively associated with increased abdominal obesity (waist circumference), hypertriglyceridemia, hyperglycemia, and decreased HDL–C." (PMID 37328862, 2023).
testis cancers (2 papers, 2021 to 2024). "LIPG increased risk of gastric and testis cancers in previous studies." (PMID 34001944, 2021).
chronic hepatitis B (1 paper, 2023). "Interestingly, immunohistochemical staining and western blotting analysis showed the increased expression of LIPG in the liver of patients with chronic hepatitis B compared with normal liver patients." (PMID 37655967, 2023). "Interestingly, LIPG expression was increased in liver tissue from patients with chronic hepatitis B compared with healthy controls." (PMID 37655967, 2023).
colon adenocarcinoma (1 paper, 2022). "Finally, we explored the correlations between LIPG expression and clinicopathological factors in TCGA Colon Adenocarcinoma (COAD) and Rectum adenocarcinoma (READ) datasets." (PMID 35108261, 2022).
colorectal tumor (1 paper, 2017). "Similarly, it is possible that the risk allele is associated with CRC by increasing levels of LIPG in colorectal tumor tissue to supply lipid precursors during tumorigenesis." (PMID 28506205, 2017).
invasive breast carcinoma (1 paper, 2022). A carcinoma that infiltrates the breast parenchyma. "In patients with invasive breast carcinoma (IBC), higher levels of LIPG and signature genes of OXPHOS were found to be correlated with the presence of DANCR in the tumors (n = 1085)." (PMID 35954428, 2022).
lipoprotein deficiency (1 paper, 2022). "Upregulation of the extracellular enzyme LIPG, which facilitates lipoprotein uptake and lipid release from HDLs, was indicative of cellular response to lipoprotein deficiency." (PMID 36010867, 2022).
melanoma (1 paper, 2016). A malignant, usually aggressive tumor composed of atypical, neoplastic melanocytes. "Of the cellular populations tested, the eight BCa cell lines expressing FoxA1 or FoxA2 had very high levels of LIPG protein compared with the melanoma MDA435 cell line and the human epithelial cell." (PMID 27045898, 2016).
thyroid cancer (1 paper, 2020). "We detect a number of recurrent fusions, such as those involving ANO3, RGS9, FUT5, CHI3L1, OR1D4, and LIPG in breast; IGF2 in colon; ETV1 in prostate; and IGF2BP3 and SIX2 in thyroid cancers." (PMID 32631391, 2020).
tumor (23 papers, 2015 to 2025). "LIPG, a cell surface lipase, has been implicated in tumor proliferation, progression, and metastasis." (PMID 40804485, 2025). "By combining RNA sequencing (RNA-seq) with ChIP-seq for active histone mark H3K27ac, we observed that a reduction in H3K27ac enrichment on HDAC6 promoter regions was associated with a reduction in HDAC6 gene expression in LIPG knockdown tumor cells." (PMID 35954428, 2022). "(E) Loss of LIPG abrogates in vivo tumor formation of MDA-MB-468." (PMID 29350614, 2018). "LIPG supports BCa cell lipid addiction and loss of its activity impairs tumour growth." (PMID 27045898, 2016). "Upregulation of LIPG in tumor cells has been shown to elevate fatty acid levels and promote lipid storage, supporting cell proliferation." (PMID 40426878, 2025). "The six‐gene diagnostic model (AIFM2, ABCG1, LIPG, DGAT2, LPCAT1, and VCP) demonstrated near‐perfect classification of tumor versus normal tissues (AUC ≈0.99 in ROC analysis; 99.8% accuracy in SVM analysis)." (PMID 40804485, 2025). "For example, DANCR regulates endothelial lipase (EL/LIPG), a pivotal modulator of tumour cell metabolism, by binding to LIPG and modulating the stable expression of the LIPG protein in TNBC cells." (PMID 38877534, 2024). "To assess the importance of LIPG for the anti-tumor effects of ZDHHC1 in CRC, we used HCT116 and SW480 cells expressing shControl, shZDHHC1, shLIPG, and shZDHHC1/shLIPG." (PMID 39069526, 2024). "ZDHHC1 silencing increased tumor growth, and LIPG silencing alone inhibited the proliferation and invasion of CRC cells." (PMID 39069526, 2024). "Oxidative stress upregulates LIPG expression and protects cells from oxidative stress by accumulating lipid droplets in tumour cells." (PMID 39191281, 2024). "Given that DANCR binds to LIPG in tumor cells, we next investigated if functional DANCR mediates LIPG expression." (PMID 35954428, 2022). "Metabolic reprogramming is a hallmark of TNBC progression, and little is known about the role of LIPG in the metabolic changes that accompany TNBC tumor growth." (PMID 35954428, 2022). "As one mechanism of LIPG in the regulation of tumor cell oxidative metabolism, LIPG mediates histone deacetylase 6 (HDAC6) and histone acetylation, which contribute to changes in IL-6 and fatty acid synthesis gene expression." (PMID 35954428, 2022). "We selected cynaroside for the present studies because the LIPG enzyme assay showed that treatment with 100 μM cynaroside caused the nearly complete inhibition of LIPG enzyme activity in MCF7OE cells and prevented tumor growth." (PMID 35954428, 2022). "The importance of LIPG for tumor cell mitochondrial metabolism prompted us to test the therapeutic potential of LIPG inhibitors." (PMID 35954428, 2022). "To analyze the interaction between DANCR and LIPG inside tumor cells, we developed an MCP-MS2 system in which GFP-tagged MCP bound to MS2 stem loop sequences that can be immunoprecipitated using antibodies to identify DANCR binding." (PMID 35954428, 2022). "To explore the mechanism by which LIPG promotes tumor cell metabolism, we stably transduced 468-WT cells with two different shRNAs that targeted LIPG (ST1 and ST2)." (PMID 35954428, 2022). "A ChIP-seq analysis showed a clear decrease in H3K27ac at the HDAC6 locus in LIPG knockdown tumor cell models, indicating that LIPG epigenetically mediates tumor cell metabolism through chromatin modifications." (PMID 35954428, 2022). "To address the impact of pharmacological inhibition of LIPG enzymatic function by XEN445 on TNBC tumor growth in vivo, we performed XEN445 therapy (50 mg/kg) on nude mice with MDA-MB-468 xenograft tumors." (PMID 32488004, 2020). "Statistically analyzing numbers of lung metastatic tumor foci in both animal groups showed that LIPG knockdown by shRNA completely abrogated in vivo lung metastasis of MDA-MB-468 cells in nude mice (p<0.01)." (PMID 29350614, 2018).